IGF1 (insulin like growth factor 1)
Diseases named in the same sentence as IGF1 in open-access papers (continued):
Sharing a sentence is not in itself a finding about the gene and the disease.
pulmonary fibrosis (continued). "Although the exact role and regulation of IGF-1 signaling in pulmonary fibrosis are awaiting for elucidation, previous studies have given some clues." (PMID 30018981, 2018). "GHK attenuates BLM-induced pulmonary fibrosis by decreasing the expression of IGF-1 and inhibiting the activation of the TGF-β1/Smads signaling pathway." (PMID 29311918, 2017). "Future studies are warranted to elucidate the role of miR-130b-3p-IGF-1-miR-1 axis in lung fibrosis." (PMID 26953888, 2016). "In an animal model IGF-1 was shown to stimulate differentiation of fibroblast into myofibrolast, one of the effector of pulmonary fibrosis." (PMID 27215343, 2016). "miR-130b-3p downregulation contributed to the activation of fibroblasts and the dysregulated epithelial-mesenchymal crosstalk by promoting IGF-1 secretion from lung epithelium, suggesting a key regulatory role for this miRNA in preventing lung fibrosis." (PMID 26953888, 2016). "Like TGFβ1, IGF1 is elevated in the lungs of patients with IPF as well as in animal models of pulmonary fibrosis." (PMID 26059457, 2015). "IGF-1 is elevated in pulmonary fibrosis and acute lung injury, where fibroblast activation is a prominent feature." (PMID 24103846, 2013). "Among these we identified the IGF-1 pathway as putatively regulated by microRNAs in lung fibrosis and showed that numbers of Igf-1 positive cells, also macrophages, were increased in the lungs of bleomycin treated mice." (PMID 23987664, 2013). "We further showed that blockade of the IGF-1 pathway in the murine bleomycin lung injury model hastened resolution of pulmonary fibrosis and increased fibroblast apoptosis." (PMID 24103846, 2013). "In conclusion, using microRNA profiling of a mini-osmotic pump model of bleomycin-induced pulmonary fibrosis, combined with gene expression profiling data, we have identified that microRNAs putatively affect the IGF-1 pathway in pulmonary fibrosis." (PMID 23987664, 2013). "In the murine bleomycin lung injury model, IGF-1 mRNA was increased three to four fold over control in pulmonary fibrosis." (PMID 24103846, 2013). "For example, in patients with systemic sclerosis (SSc), serum IGF-1 level is elevated in those with more severe skin involvement and pulmonary fibrosis." (PMID 24103846, 2013). "When alveolitis occurs, levels of growth factors such as TGF-β1, platelet-derived growth factor (PDGF), and insulin-like growth factor (IGF)-1 increase, and pulmonary fibrosis gradually develops." (PMID 18500976, 2008). "Taken together, IGF-1 may play a critical role in lung disease, especially in inflammatory disease, cancers, and lung fibrosis." (PMID 36936149, 2023). "Finally, our data using primary cultures of IPF lung fibroblasts confirm the profibrotic effect of IGF1, and hint to a possible impact on lipofibroblasts in lung fibrosis." (PMID 35741102, 2022). "Inhibiting CF alleviated AECs senescence and pulmonary fibrosis induced by IGF1." (PMID 34329195, 2021). "In addition, the expression levels of serum IGF1 were even higher in patients with high skin thickness scores or with severe pulmonary fibrosis." (PMID 34222222, 2021). "There may also exist positive feedback of IGF-1 signaling in the molecular levels that promote pulmonary fibrosis." (PMID 30018981, 2018). "The expression of IGF-1 mRNA is downregulated in lung tissues from patients with idiopathic pulmonary fibrosis (IPF) or sarcoidosis, while basal or TGF-β1-stimulated IGF-1 expression is higher in fibroblasts collected from IPF or fibrotic (Phase III or IV) sarcoidosis than health controls." (PMID 30018981, 2018). "Our findings showed that BLM stimulation could increase the expression of IGF-1 in lung tissue while GHK treatment could reverse this increase in the BLM-induced pulmonary fibrosis." (PMID 29311918, 2017).
pulmonary fibrosis (continued). "In different ways, our experiments altogether provide solid evidence that miR-130b-3p indeed plays an essential role in lung fibrosis and this role is indicated by mediating the abnormal epithelial-mesenchymal crosstalk at least in part, by modulating IGF-1 expression." (PMID 26953888, 2016). "Our findings, indicting the IGF pathway to be significantly represented in microRNA regulation of bleomycin-induced pulmonary fibrosis, coupled with increased Igf-1 levels in fibrotic lung tissue, support this line of investigation and suggest the involvement of microRNA regulation." (PMID 23987664, 2013). "In particular, microRNA regulation of genes of hepatocyte growth factor-, endothelin-1- or IGF1- signaling, and specific molecular mechanisms of cancer, may affect lung fibrosis." (PMID 23987664, 2013). "Hence, IGF-1 occupies a vital role in the onset and/or proliferation of pulmonary fibrosis." (PMID 37608885, 2023). "Mechanically, TGF-β may enhance the activation of IGF-1 to promote pulmonary fibrosis." (PMID 36936149, 2023). "Due to the link between IGF1 signaling and lung fibrosis, we decided to investigate whether treatment with recombinant human IGF1 (rhIGF1) affects the expression levels of lipofibroblast and myofibroblast markers using primary cultures of human IPF lung fibroblasts." (PMID 35741102, 2022). "IL-4-induced, macrophage-derived IGF-1 protects myofibroblasts from apoptosis via Akt signaling, which may contribute to the persistence of myofibroblasts in the Th2-deviated environment of pulmonary fibrosis." (PMID 30018981, 2018). "Although abnormal IGF-1 signaling is implicated in human diseases and in animal models of lung fibrosis, there are also evidences suggesting that IGF-1 may not play a central role in the fibrotic process." (PMID 30018981, 2018). "Numerous cytokines have been implicated in the pathogenesis of lung fibrosis, including transforming growth factor-β (TGF-β), tumour necrosis factor-α (TNF-α), platelet- derived growth factor (PDGF), insulin-like growth factor-1 (IGF-1), endothelin-1 (ET-1) and the interleukins, (IL)-1 and IL-8." (PMID 28974751, 2017). "Under pathological conditions such as idiopathic pulmonary fibrosis (IPF), alveolar epithelial cells release IGF-1, which activates IGF-1R on adjacent normal alveolar epithelial cell surfaces, and further activates downstream PI3K and AKT kinases." (PMID 39638246, 2024). "This cell profile is also associated with tissue remodeling and conditions characterized by augmented fibrosis, such as pulmonary fibrosis, due to the stimulated production of profibrotic molecules including TGF‐β, IGF‐1, and galectin‐3." (PMID 37347290, 2023). "IGF-1 invigorates fibroblast proliferation, protects myofibroblasts from apoptosis, and advocates ECM accumulation, all of which are integral processes in pulmonary fibrosis." (PMID 37608885, 2023). "Mice with bleomycin-induced lung fibrosis and human IPF lung tissue have exhibited elevated IGF-1 levels." (PMID 37608885, 2023). "M2 macrophages provide an important microenvironment for pulmonary fibrosis by secreting profibrotic substances such as CCL18, IL-10, TIMP1 (tissue inhibitors of metalloproteinases 1), TGF-β, FGF, PDGFα, IGF1, and VEGF." (PMID 35935869, 2022). "Lung tissues derived from bleomycin-treated mice and explanted IPF lungs revealed upregulation of IGF1 in parallel to downregulation of IGF1R, in addition to upregulation of several IGF binding proteins (IGFBPs) in lung fibrosis." (PMID 35741102, 2022). "IGF1 mRNA levels also increased in bleomycin-induced pulmonary fibrosis in mice and human IPF, indicating that IGF1 has a certain effect on the local production in the fibrosis disease progression." (PMID 33672678, 2021). "Several studies reported that TGF-β1 and other growth factors, such as IGF-1 and VEGF, are actively involved in the development of pulmonary fibrosis." (PMID 33123311, 2020).
pulmonary fibrosis (continued). "Employing UCN‐01 to activate FoxO3 in lung fibrosis, this agent was found to inhibit proliferation of IPF fibroblasts as well as donor fibroblasts that were stimulated by FCS, PDGF‐BB, or IGF‐1." (PMID 29217661, 2018). "In this article, we reviewed the up-to-date roles and possible mechanisms of IGF-1 signaling pathway in lung development and inflammatory diseases including BPD, pulmonary fibrosis, ALI and ARDS, asthma, COPD, and CF." (PMID 30018981, 2018). "IGF-1 and IGFBP-5 expressions are significantly reduced in ATII cells in a rat model of bleomycin-induced pulmonary fibrosis." (PMID 30018981, 2018). "On the other side, expression of IGF-1 is inhibited by Th1 cytokine IFN-γ and induced by Th2 cytokines IL-4 and IL-13, while pulmonary fibrosis is a typical Th2 response that IL-4 and IL-13 predominate." (PMID 30018981, 2018). "In a mice model of bleomycin-induced pulmonary fibrosis, three miRNAs and IGFBP3 are decreased, while IGF-1, IGFBP-5, and 8 miRNAs are increased." (PMID 30018981, 2018). "Blockade of the IGF-1/IGF-1R pathway by an IGF-1R antibody induces fibroblast apoptosis and subsequent resolution of pulmonary fibrosis." (PMID 30018981, 2018). "IGF-1 mRNA and protein levels were up-regulated in the murine BLM lung fibrosis model compared with the control group." (PMID 29311918, 2017). "It has been proved that IGF-1 plays important role in the regulation of cytokines in fibrosis, thus we measured the expression of IGF-1 in BLM-induced pulmonary fibrosis and the effect of GHK on IGF-1 expression." (PMID 29311918, 2017). "In this study, we found that IGF-1 protein levels increased after the intratracheal instillation of BLM for 21 days, suggesting that IGF-1 was involved in pulmonary fibrosis and tissue injury." (PMID 29311918, 2017). "Our mouse model suggests that BLM works via mechanisms dependent on IGF-1 to activate the TGF-β1/Smads signaling pathway, leading to pulmonary fibrosis." (PMID 29311918, 2017). "Moreover, the existing research found that metformin exhibited pleiotropic mechanisms for alleviating lung fibrosis, such as NOX4 inhibition, IGF-1 suppression, and mTOR inactivation, and so on." (PMID 36091775, 2022). "Adenoviral vector-mediated overexpression of IGF-1 in the mice lungs does not result in significant fibroblast or collagen accumulation featuring pulmonary fibrosis, but significant and prolonged inflammatory cell infiltration instead." (PMID 30018981, 2018). "IGF-1 released by alveolar macrophages (AMs) is elevated in BALF, which increases fibroblast mitogenic activity of sarcoidosis BALF that contributes to late-stage pulmonary fibrosis." (PMID 30018981, 2018). "IGF-1 may induce epithelial-mesenchymal transition (EMT) of ATII cells, an important process forming fibroblast-like, ECM-producing cells in pulmonary fibrosis." (PMID 30018981, 2018). "Subsequent studies have found that miR-130b-3p could target IGF-1, which has been reported about its elevation in fibrotic lung diseases, such as IPF, coal worker’s lung fibrosis, fibroproliferative ARDS, as well as bleomycin-induced mouse lung fibrosis." (PMID 26953888, 2016). "Additionally, previous studies showed that lung macrophages and epithelium of IPF patients expressed high level of IGF-1, and IGF-1 was putatively regulated by miRNAs in bleomycin-induced mouse lung fibrosis." (PMID 26953888, 2016). "Furthermore, activation of the IGF-1/IGF-1R axis led to the generation of reactive oxygen species (ROS), which promotes epithelial-mesenchymal transition (EMT) in alveolar epithelial cells, thereby accelerating pulmonary fibrosis." (PMID 39638246, 2024).
Glucose intolerance (52 papers, 2005 to 2025). Glucose intolerance (GI) can be defined as dysglycemia that comprises both prediabetes and diabetes. "Several in vivo studies found that Mn deficiency caused glucose intolerance and reduced insulin secretion, manifested by decreased circulating IGF-1 and insulin, and increased IGFBP3." (PMID 38132161, 2023). "Low concentrations of IGF-1 were proven to be strictly linked to growing risk of glucose intolerance and the development of DM II." (PMID 34208601, 2021). "In patients in whom the reduced Si is the main cause behind glucose intolerance the reduction of GH/IGF-1 induced by the SSA would increase Si more than the direct insulin inhibition with the result of improved glucose tolerance." (PMID 31620090, 2019). "In the general population and experimentally, IGF1 deficiency leads to glucose intolerance and T2D, the conditions rare among the studied RA patients." (PMID 31327319, 2019). "Nonetheless, low IGF-1 circulating levels are also associated with reduced insulin sensitivity, glucose intolerance, and T2D." (PMID 26733412, 2016). "Moreover, genetic studies demonstrate that low IGF-1 is associated with both T1DM and T2DM and decreased IGF-1 increases the risk of glucose intolerance and T2DM." (PMID 30983995, 2019). "Similarly, in humans, IGF-1administration was found to increase glucose uptake and inhibit hepatic glucoseproduction in healthy subjects, and low serum IGF-1 levels werefound associated with glucose intolerance." (PMID 20157552, 2009). "Circulating IGF-1 (cIGF-1) and its interactions with IGF Binding Protein 1 (IGFBP-1) are important determinants of glucose homeostasis, potentially indicating a protective role of IGF-1 against the development of glucose intolerance." (PMID 34208601, 2021). "A high p44:FLp53 ratio led to changes in important ageing factors such as the IGF-1 (insulin-like growth factor 1) signalling pathway, as well as developing hypoinsulinemia and glucose intolerance." (PMID 32585821, 2020). "We also found a significant positive correlation between β-cell function and IGF-1 in patients with glucose intolerance as well as in those with NGT." (PMID 31736874, 2019). "In sum, expression of the RIP::IGF-1 transgene partially corrected glucose intolerance, rescued insulin sensitivity, partially ameliorated the aberrantly heightened gluconeogenic production, and reduced fasted blood glucose content in female GHR-KO mice." (PMID 25244225, 2014). "Elevated hepatic IGFBP1 may have neutralized IGF-1 in the livers of Cnot4 Het mice, leading to hepatic insulin resistance and inhibition of glucose uptake, and eventually augmenting glucose intolerance in Cnot4 Het mice." (PMID 40424271, 2025). "Defects in insulin and IGF1 signaling pathways were also found to be responsible for decompensation of β‐cell proliferation and mass, which contributes to disturbance of insulin secretion and glucose intolerance in T2DM." (PMID 36891946, 2023). "IGF-1 rather than GH was a significant risk factor for glucose intolerance after adjusting for clinical data." (PMID 34208601, 2021). "Low IGF-1 levels have been shown to forecast glucose intolerance and T2D." (PMID 33905470, 2020). "Higher IGF-1 bioavailability may protect the onset of ischemic heart disease and glucose intolerance in T2D patients, thus improving metabolic control and preventing vascular complications." (PMID 33905470, 2020). "Thus, we have found that mice carrying a Vav2 mutant protein with reduced catalytic activity exhibit impaired IGF1- and insulin-mediated PI3Kα signaling, reduced muscle mass, and increased glucose intolerance." (PMID 33199701, 2020). "Therefore, we speculated that the progressive glucose intolerance of PEE offspring from PW12 to 24 might be due to the loss of sensitivity to endogenous insulin and IGF1." (PMID 30778335, 2019).
Glucose intolerance (continued). "Mn supplementation improves glucose intolerance and prevents diet-induced diabetes by increasing insulin secretion and the expression of IGFR and IGF-1 in the hypothalamus, as well as increasing the expression of MnSOD." (PMID 38132161, 2023). "Therefore, we postulate that there was a difference in predisposition to glucose intolerance after birth attributable to the protective effect of estrogen, and not as a result of the effect of the decrease in GH and/or IGF-1 levels due to fetal programming by nicotine." (PMID 34177815, 2021). "Interestingly, glucose intolerance could be improved when IGF-1 was systemically administered." (PMID 26733412, 2016). "In contrast, studies on glucose intolerance and IGF-1 have been conducted using knockout mice lacking the insulin receptor substrate 2 (IRS2) gene." (PMID 33746806, 2021). "In addition, IGF-1 was significantly correlated with IR in patients with NGT but not in patients with abnormal glucose tolerance, possibly due to HOMA's limited value for predicting IR calculated by a wide FPG range in patients with glucose intolerance." (PMID 31736874, 2019). "Moreover, global deletion of IGF-1 gene expression in mice does not result in glucose intolerance." (PMID 26733412, 2016).